GNG7 (G protein subunit gamma 7)
Diseases named in the same sentence as GNG7 in open-access papers (continued):
Sharing a sentence is not in itself a finding about the gene and the disease.
oesophageal cancer (5 papers, 2008 to 2021). "Loss of heterozygosity in the GNG7 region at 19p13.3 was examined in 42 oesophageal cancer cases using two microsatellite markers." (PMID 18219292, 2008). "In addition, GNG7 expression was significantly associated with the presence of miR328 in oesophageal cancer cell lines, which suggests that this microRNA might be a regulator of GNG7 expression." (PMID 18219292, 2008). "In oesophageal cancer, tumors with high GNG7 expression are less invasive than those with low GNG7 expression in vitro and in vivo." (PMID 34221006, 2021). "Extending that observation, we also found GNG7 promoter hypermethylation in oesophageal cancer tissues." (PMID 18219292, 2008). "In this study, we demonstrated that expression of GNG7 was frequently (82% of cases) and strongly suppressed in oesophageal cancer tissues compared with normal oesophageal tissues." (PMID 18219292, 2008). "TaqMan quantitative real-time PCR was performed to determine the clinical significance of GNG7 expression in 55 cases of oesophageal cancer." (PMID 18219292, 2008). "Methylation of the GNG7 promoter region was assessed in 42 oesophageal cancer patients (paired tumour and normal DNA)." (PMID 18219292, 2008). "In the current study, we significantly expanded that work with additional cases and analysed clinicopathologic information to determine the precise role of GNG7 in oesophageal cancer." (PMID 18219292, 2008). "In oesophageal cancer, GNG7 was lowly expressed in tumor tissues and low expression of GNG7 was significantly associated with poor prognosis, which could be used as a potential biomarker for cancer diagnosis and prognostic evaluation." (PMID 33727922, 2021). "Interestingly, in 45 of 55 oesophageal cancer tissue specimens (82% of total), the level of GNG7 suppression was at least 80% compared to the level of corresponding normal tissue specimens." (PMID 18219292, 2008). "Furthermore, GNG7-transfected oesophageal cancer cells were analysed in laboratory studies at genomic and epigenetic levels." (PMID 18219292, 2008). "We analysed the mechanism by which GNG7 expression was reduced in oesophageal cancer." (PMID 18219292, 2008). "In the current study, we examined the clinical significance of diminished GNG7 expression in oesophageal cancer cases and determined whether its expression was altered at the genomic level, mRNA level, epigenetic level or the microRNA level." (PMID 18219292, 2008). "We showed that expression of GNG7 in oesophageal cancer cell lines could be restored by treatment with the demethylating drug 5-AZAC." (PMID 18219292, 2008). "Furthermore, we divided 55 oesophageal cancer cases into two groups based on the median relative expression value for GNG7 (T/N=0.32)." (PMID 18219292, 2008). "Since the expression of GNG7 was associated with the depth of tumour invasion, the transwell invasion assay was performed to determine whether invasive activity was directly mediated by expression of GNG7 in oesophageal cancer cell lines." (PMID 18219292, 2008). "In preliminary studies, we evaluated the expression of GNG7 in 10 oesophageal cancer patients." (PMID 18219292, 2008). "In summary, we demonstrated that GNG7 was frequently and strongly suppressed in oesophageal cancer." (PMID 18219292, 2008). "GNG7 suppression represents a new prognostic indicator in cases of oesophageal cancer." (PMID 18219292, 2008). "Thus, GNG7 suppression was partially related to LOH in oesophageal cancer." (PMID 18219292, 2008). "However, an epigenetic alteration may also explain the reduced expression of GNG7 in oesophageal cancer." (PMID 18219292, 2008). "The significance of GNG7 expression in oesophageal cancer is unknown." (PMID 18219292, 2008). "Therefore, based on these findings, we suggest that the hypermethylation of the GNG7 promoter might be an early event in the progression of oesophageal cancer." (PMID 18219292, 2008).
oesophageal cancer (continued). "In our oesophageal cancer study, LOH in GNG7 region (19p13.3) was detected in 10 out of 40 patients (25%)." (PMID 18219292, 2008).
glioma (3 papers, 2021 to 2022). A benign or malignant brain and spinal cord tumor that arises from glial cells (astrocytes, oligodendrocytes, ependymal cells). "The positive clustering results of this study might be attributed to some characteristics of glioma tissue, such as the glioma-specific 1p19q co-deletion that affected the expression of GNB1, GNG5, GNG7, GNGN8, and GNG12." (PMID 34222011, 2021).
lymphoma (3 papers, 2019 to 2024). A malignant (clonal) proliferation of B- lymphocytes or T- lymphocytes which involves the lymph nodes, bone marrow and/or extranodal sites. "GNG7, AXIN2, HIF1A, FGF2 and PPAP2B are found upregulated in our study in the same way as it is found in association with lymphoma disease according to literature." (PMID 30679748, 2019).
Obesity (3 papers, 2019 to 2025). Accumulation of substantial excess body fat. "Until now, the specific roles of ANO2, CAMK2D, SLC8A1, PDE2A, CALML3, GNG7, and CALML6 genes in olfactory-related dietary patterns and obesity in humans have not been apparently explored; therefore, further investigation in these research areas is warranted." (PMID 31057674, 2019).
colon adenocarcinoma (2 papers, 2022 to 2023). "The results revealed that compared with normal tissues, the expression level of GNG7 was significantly lower in several malignancies, including STAD, colon adenocarcinoma, rectum adenocarcinoma, and others (P < 0.01)." (PMID 36863706, 2023).
colon cancer (2 papers, 2022 to 2025). "Notably, PDX1 and GNG7 were common to both rectal and colon cancer analyses, with GNG7 also ranking among the top ten genes in colon cancer." (PMID 40565513, 2025).
Hodgkins lymphoma (2 papers, 2013 to 2023). A heterogeneous group of malignant lymphoid neoplasms of B-cell origin characterized histologically by the presence of Hodgkin and Reed-Sternberg (HRS) cells in the vast majority of cases. "GNG7 showed homozygous deletions in cell lines of classical Hodgkins lymphoma." (PMID 23403885, 2013).
kidney cancer (2 papers, 2022 to 2023). Primary or metastatic malignant neoplasm involving the kidney. "We further elaborated the close relationship between 7 immunoprognostic genes and GNG7, and calculated the risk scores of these genes and combined them with clinical information to construct a model that can assess the prognosis of kidney cancer." (PMID 37704946, 2023). "However, differing from previous studies, we combined the genes associated with GNG7 in kidney cancer cell lines and further elaborated the potential mechanisms and immune characteristics of these genes in kidney cancer by GO and KEGG gene enrichment analysis." (PMID 37704946, 2023). "Here in this study, we first examined the oncogenic role of GNG7 in CCRCC, then further analyzed the relationship between the GNG7 gene and immune infiltrating cells in CCRCC and also discussed the relationship between GNG7-related genes in the immune function pathway in kidney cancer cell lines." (PMID 37704946, 2023).
preeclampsia (2 papers, 2021). Preeclampsia is a hypertensive disorder of pregnancy that is characterized by new-onset hypertension with proteinuria presenting after 20 weeks of gestation, and depending on mild or severe forms may initially present with severe headache, visual disturbances, and hyperreflexia. "Besides, GNG7 silencing promoted the proliferation and differentiation of placental cytotrophoblasts in preeclampsia rats via activating the mTOR signaling pathway." (PMID 33727922, 2021).
Stroke (2 papers, 2019 to 2023). Sudden impairment of blood flow to a part of the brain due to occlusion or rupture of an artery to the brain. "Using a pathway analysis, we found deletions in GNB1, PRKCZ, and GNG7 genes related to the alpha-adrenergic receptor signaling pathway that play a major role in determining the risk of an AF-related stroke." (PMID 30857284, 2019).
acne (1 paper, 2021). An inflammatory process of the sebaceous glands which is characterized by comedones, nodules, papules and/or pustules on the skin. "The presence of GNG7 mRNA could be visualized in sebaceous glands of normal skin, while in acne samples, in which elevated miR-146a levels were shown, it could not be detected." (PMID 34728702, 2021). "Our findings suggest, that miR-146a could be a potential player in acne pathogenesis by regulating inflammation, inducing proliferation and, through the indirect down-regulation of GNG7, promoting the lipid production of sebocytes." (PMID 34728702, 2021).
Alzheimer disease (1 paper, 2020). A progressive, neurodegenerative disease characterized by loss of function and death of nerve cells in several areas of the brain leading to loss of cognitive function such as memory and language. "These loci were enriched in genes with functions related to Alzheimer's disease and cognitive decline, including GNB5, GNG7 and PKN3 (p < 0.05)." (PMID 32525932, 2020).
asthma (1 paper, 2024). "In total, 6 genes were upregulated (e.g. CCL3L1, CCL4L2, GPR82) and 20 were downregulated (e.g. JUN, IFITM3, DUSP1, GNG7) in peripheral eosinophils of COPD patients compared to asthma." (PMID 39422548, 2024).
breast tumor (1 paper, 2023). "The mRNA expression level of ADHFE1 and GNG7 was significantly down-regulated in the primary breast tumor." (PMID 36969015, 2023).
cocaine dependence (1 paper, 2024). A psychologically and socially impaired state, with or without physiological changes, that develops as a result of using cocaine and which leads to compulsive behaviors to acquire the substance. "Additionally, miR-504-3p has also been directly linked to Gng7 expression in the hippocampus in response to chronic alcohol administration and has been associated with nicotine, and cocaine dependence, suggesting a possible role in addictive disorders." (PMID 38764487, 2024).
colorectal adenocarcinoma (1 paper, 2025). The most common type of colorectal carcinoma. "Conversely, high GNG7 expression correlates with a poorer prognosis in colorectal adenocarcinoma (COAD) (P<0.05)." (PMID 40496619, 2025).
complex regional pain syndrome (1 paper, 2019). A chronic pain syndrome characterized by a disproportionate spontaneous or stimulus-induced pain, accompanied by a variably mixed myriad of autonomic and motor disorders including symptoms such as swelling, allodynia, skin blood supply and trophic disturbances. "There is a network centered on GNG7, that may be involved in connectivity/signaling, comprising HTR2A, EDN1, PNOC (involved in pain signaling) and CALCA (involved in Reflex Sympathetic Dystrophy and Complex Regional Pain Syndrome)." (PMID 30755720, 2019).
coronary heart disease (1 paper, 2023). "Lovastatin, on the other hand, is a co-targeted drug for Ddit4l and Gng7 and is commonly used to treat coronary heart disease and hypercholesterolemia." (PMID 38089628, 2023).
Hypertension (1 paper, 2023). The presence of chronic increased pressure in the systemic arterial system. "Perindopril, a co-target of Chrna2 and Gng7, is an angiotensin-converting enzyme inhibitor indicated for the treatment of hypertension." (PMID 38089628, 2023).
methamphetamine dependence (1 paper, 2025). A drug dependence that is a psychological dependency on the regular use of methamphetamine. "In contrast, ROC curve analysis indicated no diagnostic significance for methylation in the ATP6V1C1, CIZ1, GNG7 and LIAS genes concerning methamphetamine dependence." (PMID 41368944, 2025).
pituitary tumor (1 paper, 2022). A benign or malignant neoplasm affecting the pituitary gland. "Further studies are needed to clarify the role and relevance of C7orf50, GNG7, and BAHCC1 genes—which have been found to be methylated—in pituitary tumor biology, oncogenesis, and clinical expression." (PMID 35432200, 2022). "We also found three hypermethylated genes (C7orf50, GNG7, and BAHCC1) involved in tumorigenesis processes and potentially influencing pituitary tumor pathophysiology." (PMID 35432200, 2022). "Finally, we found three hypermethylated genes (C7orf50, GNG7, and BAHCC1), involved in tumorigenesis processes, whose role could be related to pituitary tumor pathophysiology." (PMID 35432200, 2022).
renal carcinoma (1 paper, 2023). A carcinoma arising from the epithelium of the renal parenchyma or the renal pelvis. "The immune relevance of GNG7 and related genes was explored using renal cancer data from CCLE and TISIDB database." (PMID 37704946, 2023). "Based on the 32 renal cancer cell lines in the CCLE database, 207 genes significantly related to GNG7 were obtained upon the threshold of P < 0.05." (PMID 37704946, 2023).
small cell lung carcinoma (1 paper, 2020). Small cell lung cancer (SCLC) is a highly aggressive malignant neoplasm, accounting for 10-15% of lung cancer cases, characterized byrapid growth, and early metastasis.
tumor (30 papers, 2008 to 2025). "The results of open-access database analyses suggested that GNG7 is downregulated in GC; this downregulation was associated with tumor progression." (PMID 36863706, 2023). "Meanwhile, the multivariate Cox regression analysis also revealed that low expression of GNG7, similar to Primary therapy outcome and Residual tumor, was an independent risk factor for the prognosis of LUAD patients." (PMID 36159963, 2022). "The prognostic significance of GNG7 expression associated with immune cell infiltration was investigated using the Tumor Immune Estimation Resource 2.0 (TIMER2.0) and the Kaplan-Meier plotter database." (PMID 36159963, 2022). "Overall, these results indicate that GNG7 is a potential tumor suppressor that is associated with multiple functional biological processes in BrCa." (PMID 33727922, 2021). "Regarding the clinical pathological parameters, we found that low expression of GNG7 was significantly associated with tumor grade." (PMID 30945310, 2019). "Clinicopathologic analysis of the high- and low-expression groups showed that low GNG7 expression was significantly associated with greater depth of tumour invasion (P<0.05)." (PMID 18219292, 2008). "Low GNG7 expression was associated with enhanced tumor growth and poor prognosis in LUAD patients." (PMID 40496619, 2025). "Leveraging data from the TCGA databases, we concentrated on the significance of GNG7 expression in cancer, analyzing its expression in normal versus tumor tissues, association with gene mutations and CNVs (Copy Number Variations), and correlation with cancer staging and patient survival." (PMID 40496619, 2025). "Together, these results suggest that GNG7 may contribute to the remodeling of the immune microenvironment in LUAD through promoting the infiltration of a variety of tumor-associated immune cells and influencing antigen presentation." (PMID 36159963, 2022). "Rescue experiment proven that enforced expression of GNG7 could partial abrogated the tumor-promoting effect caused by miR-19b-3p." (PMID 34635014, 2021). "Given GNG7’s role in intracellular signaling and actin cytoskeleton regulation, it is plausible that it affects tumor immune evasion by modulating cytokine secretion and immune cell trafficking, thereby altering immune recognition and response." (PMID 40496619, 2025). "Establishing different cell models will be crucial for this purpose, allowing for more precise exploration of GNG7’s function in diverse tumor microenvironments." (PMID 40496619, 2025). "qPCR analysis of 34 LUAD samples revealed a significant decrease in GNG7 expression in tumor tissues compared to adjacent normal tissues (P < 0.05)." (PMID 40496619, 2025). "Our study observed that low expression of GNG7 is positively correlated with poorer OS, suggesting that GNG7 exerts a protective role by inhibiting tumor growth and facilitating apoptosis of tumor cells." (PMID 40496619, 2025). "We observed that GNG7 expression significantly correlates with the infiltration levels of various immune cells in the tumor microenvironment." (PMID 40496619, 2025). "GNG7 as one of the key intracellular genes regulating division, growth, and apoptosis is low-expressed in different types of tumor tissues." (PMID 39959839, 2025). "The findings revealed that GNG7 expression levels in tumor tissues were notably lower compared to those in normal tissues (P<0.0001)." (PMID 40496619, 2025). "We believe that these investigations will contribute to a deeper understanding of the role of GNG7 in tumor-immune interactions, potentially leading to the development of more effective personalized treatment strategies for CCRCC patients." (PMID 37704946, 2023).